SYBU (syntabulin)
Description:
Part of a kinesin motor-adapter complex that is critical for the anterograde axonal transport of active zone components and contributes to activity-dependent presynaptic assembly during neuronal development.
Synonyms: GOLSYN; KIAA1472; FLJ20366; OCSYN; SNPHL
Tractability: Antibody: UniProt predicts a signal peptide or a membrane-spanning region. PROTAC: ubiquitination databases record sites on it; its protein half-life has been measured.
Gene: Protein-coding gene on chromosome 8 (109,573,978 to 109,691,791, reverse strand). Ensembl gene ENSG00000147642.
Subcellular location: Cytoplasm, cytoskeleton (Isoform 1); Cytoplasmic vesicle; Golgi apparatus membrane (Isoform 3); Golgi apparatus membrane (Isoform 4); Golgi apparatus membrane (Isoform 5)
Subcellular location (Human Protein Atlas): Vesicles
Gene Ontology:
Molecular function: protein binding
Biological process: axonal transport of mitochondrion; synapse maturation; anterograde neuronal dense core vesicle transport; positive regulation of insulin secretion involved in cellular response to glucose stimulus; regulation of synaptic activity
Cellular component: microtubule; mitochondrion; vesicle; cytoplasmic microtubule; axon cytoplasm; cytoplasmic vesicle; cytoskeleton; Golgi membrane
Genetic constraint (gnomAD): Loss-of-function variants: 21 observed, 33.85 expected, observed/expected ratio (o/e) 0.62, 90% interval 0.44 to 0.89. The upper end of that interval is the gene's LOEUF score, 0.89, which puts it in group 3 of 6, group 1 being the genes least tolerant of losing a copy. Missense variants: 765 observed, 866.88 expected, observed/expected ratio (o/e) 0.88, 90% interval 0.83 to 0.94. Synonymous variants: 318 observed, 335.09 expected, observed/expected ratio (o/e) 0.95, 90% interval 0.87 to 1.04.
Homologues: Orthologues: chimpanzee SYBU (99% identical), macaque SYBU (98% identical), rabbit SYBU (88% identical), rat Sybu (86% identical), mouse Sybu (85% identical), guinea pig SYBU (84% identical), dog SYBU (83% identical), pig SYBU (83% identical), tropical clawed frog sybu (57% identical), zebrafish sybu (42% identical). Paralogues in human: SNPH (30% identical).
Diseases named in the same sentence as SYBU in open-access papers:
SYBU is named in the same sentence as 12 diseases in open-access papers, as found by Europe PMC text mining. Sharing a sentence is not in itself a finding about the gene and the disease. The quoted sentences say what the papers report.
autism (2 papers, 2023 to 2024). Persistent deficits in social interaction and communication and interaction as well as a markedly restricted repertoire of activity and interest as well as repetitive patterns of behavior. "A recent whole exome sequencing study identified an autism-linked de novo missense variant (Arg59Gln) in the human SYBU gene." (PMID 38568173, 2024). "A recent study found that mice with syntabulin specifically knocked out of the central nervous system exhibited core symptoms similar to autism." (PMID 37349285, 2023).
brain injury (1 paper, 2023). Acute and chronic (see also brain INJURIES, CHRONIC) injuries to the brain, including the cerebral hemispheres, CEREBELLUM, and brain STEM. "Western blotting (WB) showed that syntabulin was significantly upregulated in TLE patients compared with non-epileptic traumatic brain injury (TBI) patients." (PMID 37349285, 2023).
epilepsy (1 paper, 2023). A brain disorder characterized by episodes of abnormally increased neuronal discharge resulting in transient episodes of sensory or motor neurological dysfunction, or psychic dysfunction. "Our current study identified a protective role for the microtubule-associated protein syntabulin in epilepsy and revealed for the first time the molecular mechanism of syntabulin-dependent STX1B synaptic trafficking in maintaining E/I balance in epilepsy." (PMID 37349285, 2023). "Knockdown of syntabulin increased susceptibility and severity of epilepsy, whereas overexpression of syntabulin had the opposite effect." (PMID 37349285, 2023). "Next, we tested the effect of syntabulin on susceptibility to epilepsy in mice." (PMID 37349285, 2023). "In summary, syntabulin plays a protective role in epilepsy by maintaining a proper E/I balance in the hippocampus." (PMID 37349285, 2023). "Next, the upstream transcription factor- transcription factor activating enhancer binding protein 2 α (TFAP2A), which is highly matched with syntabulin and notably related to epilepsy, was predicted by JASPAR software." (PMID 37349285, 2023). "To explore the role of syntabulin in epilepsy, we first examined the expression of syntabulin in TLE patients and kainic acid (KA) mouse model." (PMID 37349285, 2023). "These evidences suggest that TFAP2A regulates syntabulin expression in epilepsy and STX1B expression in synaptosomes, and affects neural excitability." (PMID 37349285, 2023). "According to JASPAR software prediction and verification, we found that syntabulin is regulated by transcription factor TFAP2A in epilepsy." (PMID 37349285, 2023). "Knockdown of syntabulin resulted in the aggravation of the epileptic phenotype, which further suggested that the altered expression of syntabulin plays an important role in epilepsy." (PMID 37349285, 2023). "In conclusion, our results suggest that syntabulin is transcriptionally activated in epilepsy and subsequently involved in the development of epilepsy." (PMID 37349285, 2023). "We found that syntabulin increased in the brain tissue of epilepsy animal model, suggesting that syntabulin may be regulated by upstream transcription factors." (PMID 37349285, 2023). "We next queried the potential mechanisms by which syntabulin affects epilepsy." (PMID 37349285, 2023). "Spontaneous recurrent seizures (SRSs) are an important feature of epilepsy, and we next examined whether altering syntabulin affects SRSs." (PMID 37349285, 2023). "This hypothesis is confirmed by our study, which provides evidence that syntabulin protein expression is elevated in brain tissue from epilepsy patients and animal models of epilepsy and plays a compensatory protective role." (PMID 37349285, 2023). "Here, using biochemical, behavioral, and electrophysiological approaches, we show that syntabulin plays a protective role in epilepsy by interacting with STX1B, but not STX1A, and mediating its delivery to the synapse." (PMID 37349285, 2023). "In line with to these findings, our results suggest that syntabulin positively regulates the localization and expression of STX1B at synapses and subsequently affects synaptic transmission to participate in the development of epilepsy." (PMID 37349285, 2023). "Overall, we show for the first time that syntabulin transits more STX1B (but not STX1A) to the excitatory/inhibitory presynaptic membrane in epilepsy, suppressing neuronal hyperexcitability." (PMID 37349285, 2023). "These experiments suggested that syntabulin may affect epilepsy by transporting more STX1B rather than affecting STX1B expression." (PMID 37349285, 2023). "In addition, whether other potential mechanisms such as epigenetic modifications also affect syntabulin mRNA expression in epilepsy cannot be ruled out." (PMID 37349285, 2023).
epilepsy (continued). "Furthermore, syntabulin-dependent STX1B trafficking and synaptic delivery is critical for presynaptic neurotransmitter release and E/I balance, which protects the brain from epilepsy and may be a potential therapeutic target." (PMID 37349285, 2023).
hepatocellular carcinoma (1 paper, 2023). A malignant tumor that arises from hepatocytes. "It has been reported that SYBU, a microtubule-associated protein, is overexpressed in hepatocellular carcinoma (HCC), which results in disrupted cell cycle and increased proliferation." (PMID 37900178, 2023).
viral infection (1 paper, 2016). "Western blotting analysis confirmed that after viral infection, endogenous syntabulin expression was successfully knocked down and YFP-tagged PICK1 was expressed." (PMID 26868290, 2016).
infection (1 paper, 2016). The state of being infected such as from the introduction of a foreign agent such as serum, vaccine, antigenic substance or organism. "First, we knocked down endogenous syntabulin by using lentiviral infection, and then challenged the neurons with distinct pH environments." (PMID 26868290, 2016). "To examine syntabulin’s regulatory effect on ASIC2 in neurons, we used lentiviral infection to knockdown endogenous syntabulin expression and then checked ASIC2 levels." (PMID 26868290, 2016).
tumor (1 paper, 2020). "Specifically, we show that LINC00174 favors the expression of SYBU, FEM1B, and SCD5 genes by sponging miR-145-5p, a well-known tumor suppressor microRNA downregulated in a variety of tumors, included TETs." (PMID 33161413, 2020).
SYBU also shares sentences with these, for which no sentence is quoted: neurological diseases (2 papers); carcinoma (1); central nervous system diseases (1); Cognitive impairment (1); thymoma (1).